RNU6-136P (RNA, U6 small nuclear 136, pseudogene)
Gene: Small nuclear RNA gene on chromosome 2 (218,589,214 to 218,589,320, reverse strand). Ensembl gene ENSG00000207393.
Homologues: Orthologues: macaque U6 (96% identical), guinea pig U6 (83% identical), pig U6 (75% identical), dog U6 (74% identical), guinea pig U6 (73% identical), rat LOC120093311 (72% identical), mouse Gm24750 (71% identical), rabbit U6 (64% identical). Paralogues in human: RNU6-26P (86% identical), RNU6-1131P (85% identical), RNU6-1175P (85% identical), RNU6-1200P (85% identical), RNU6-1201P (85% identical), RNU6-15P (85% identical), RNU6-19P (85% identical), RNU6-209P (85% identical), RNU6-949P (85% identical), RNU6-1011P (84% identical), RNU6-10P (84% identical), RNU6-12P (84% identical), and 1283 more.